PIK3CA (phosphatidylinositol-4,5-bisphosphate 3-kinase catalytic subunit alpha)
Diseases named in the same sentence as PIK3CA in open-access papers (continued):
Sharing a sentence is not in itself a finding about the gene and the disease.
breast cancer (continued). "Somatic alteration of the phosphatidylinositol-4,5-bisphosphate 3-kinase catalytic subunit alpha (PIK3CA) gene is one of the most prevalent driver genes in breast cancer, occurring at a frequency of 20–40%." (PMID 33386585, 2021). "Alpelisib, a PI3Kα specific inhibitor, in combination with fulvestrant prolonged progression-free survival among patients with PIK3CA-mutated, hormone receptor (HR)-positive, HER2-negative advanced breast cancer who had received endocrine therapy previously." (PMID 33669867, 2021). "Here, the authors show that INPP4B enhances proliferation and growth of PIK3CA-mutant ER+ breast cancers by promoting PI3Kα-dependent late endosome formation and trafficking that leads to the activation of Wnt/β-catenin signalling." (PMID 34035258, 2021). "Combination of MK-2206 with the aromatase inhibitor anasterozole appears to be unable to enhance the efficacy of anasterozole in patients with PIK3CA-mutant ER+/Her2− breast cancer." (PMID 34419139, 2021). "Various genomic alterations and genomic signatures, including ERBB2 amplification, mutations in PIK3CA, AKT1, and ESR1, and tumor mutational burden (TMB), have become important biomarkers for treatment selection in breast cancer (BC)." (PMID 33968723, 2021). "In our study, the frequency of PIK3CA and PTEN mutations was 20%, which is similar to other published breast cancer studies." (PMID 32886682, 2020). "The incidence of PIK3CA mutations has been estimated at 36%‐45% of HR+, HER2‐negative breast cancers; up to 40% of HER2‐positive breast cancers; and 9%‐14% of triple‐negative breast cancers." (PMID 32697890, 2020). "Lastly, CDK4/6 inhibitors were also shown to be effective in sensitizing PIK3CA mutant breast cancer cells to PI3K inhibitors, demonstrating efficacy in overcoming intrinsic and acquired resistance to PI3K inhibition." (PMID 32226926, 2020). "Both breast cancer and HNSCC cell lines carrying PIK3CA mutations or wild-type PIK3CA respond to IQ3 peptide treatment." (PMID 32923516, 2020). "Our study showed that in vitro Rlip deficiency inhibits EGF endocytosis and downstream signaling from WNT5A to ERK and PIK3CA, which are key proteins involved in the oncogenesis and natural history of breast cancer." (PMID 32498332, 2020). "In a previous study of 22 newly diagnosed breast cancer patients, positive PIK3CA E542K status was determined in one tissue biopsy sample, one patient was identified as positive for E545K, and three patients were confirmed to carry a H1047R mutation." (PMID 33051521, 2020). "CLOVES syndrome can be treated with the PIK3CA inhibitor alpelisib, which was developed for PIK3CA-mutant breast cancer." (PMID 32066498, 2020).
breast cancer (continued). "Some studies report that PIK3CA mutations can inactivate the downstream components, such as TORC1, which can generate a better outcome in endocrine-resistant breast cancer." (PMID 32461963, 2020). "The study demonstrated significant activity of alpelisib in PIK3CA-mutant HR+/HER2− breast cancer compared with the placebo." (PMID 32886682, 2020). "PIK3CA mutations were increased overall in metastatic vs. primary sites (32.1 vs. 26.9%, p < 0.0001), specifically in HR-positive HER2-positive breast cancer (44.1 vs. 25.2%, respectively, p = 0.002) and TNBC (21 vs. 14.3%, respectively, p = 0.0002)." (PMID 32983983, 2020). "We also found protective associations between higher GReX of AURKA (20q13.2), PIK3CA (3q26.32), and SERPINB5 (18q21.33) and lower risk of breast cancer mortality." (PMID 32079541, 2020). "In a second model, MCF7 (ER+/HER2−; PIK3CA-mt) breast cancer cell line xenografts were conditioned through a long-term continuous treatment to progress on palbociclib monotherapy." (PMID 32795346, 2020). "PIK3CA inhibitors are now in clinical use in breast cancer and are being actively investigated in other tumor types." (PMID 31941061, 2020). "On the other hand, PIK3CA activated by its own receptor or by insulin growth factor 1 (IGF-1) stimulates the proliferation of neoplastic cells in breast cancer." (PMID 32629823, 2020). "Although the magnitude of the effect was variable, we observed a similar pattern of cell killing when we tested these combinations in one additional PIK3CA-mutant breast cancer cell line, namely BT-474." (PMID 32439931, 2020). "In particular, breast cancer patients with the FGFR1 amplification frequently harbor activating alterations in the PIK3CA gene." (PMID 33081025, 2020). "Poor prognosis influenced by ALDH1 was described in the metabolic pathway of PIK3CA/AKT/mTOR of breast cancer concerning grading and metastases." (PMID 32695508, 2020). "In this study, we demonstrate that a HER2 inhibitor insufficiently suppresses p4EBP1 as well as pS6 in PIK3CA-mutant HER2+ breast cancer cell lines, and that these cells are resistant to the HER2 inhibitor." (PMID 33303839, 2020). "PIK3CA encodes the catalytic p110a subunit of PI3-kinase and is mutated in 30–40% of all breast cancer." (PMID 33322643, 2020). "While PIK3CA alterations occur in 36% or more of breast cancer patients there are other relevant biomarkers to consider in these patients, including ERBB2, BRCA1, BRCA2, NTRK, and MSI (or mismatch repair deficiency)." (PMID 32976510, 2020). "PIK3CA, the gene encoding PI3K catalytic subunit p110α, is mutated in 20%‐40% of breast cancer patients." (PMID 32697890, 2020).
breast cancer (continued). "Gain-of-function mutations in PIK3CA (encoding p110α) that activate the PI3K cascade are highly prevalent in a number of malignancies, including up to 40% of breast cancer patients and as many as 53% of endometrial cancer patients." (PMID 32630372, 2020). "We therefore knocked down PTEN expression, using a small hairpin RNA (shRNA) mir-based system (PTEN KD), or knocked-out PTEN expression using CRISPR-Cas9 (PTEN KO), in two ER+PIK3CA-mutant breast cancer cell lines, T47D (H1047R) and MCF7 (E545K)." (PMID 32976773, 2020). "Several mechanisms of trastuzumab resistance have been identified in breast cancer, one of which is increased signaling through the PI3-kinase pathway caused by gain-of-function PIK3CA mutations or inactivation of PTEN." (PMID 33375706, 2020). "Multiple somatic driver mutations were identified, all previously associated with the tumor type in which the mutation was identified, such as BRAF (c.1799T > A, p.Val600Glu) in CRC and melanoma, and PIK3CA (c.1624G > A, p.Glu542Lys) in breast cancer." (PMID 33258446, 2020). "A precise understanding of the role of PIK3CA in IBC development will usher in a new era for breast cancer prevention and therapy." (PMID 32410843, 2020). "Accumulating evidence suggests that FGF signaling induced by FGFR1/2 amplification attenuates the response to PI3K blockage in PIK3CA-mutant breast cancer." (PMID 32907621, 2020). "Point mutations in PIK3CA, which activate the PI3K enzyme and signalling pathway, are observed in 20–40% of breast cancer cases." (PMID 33051521, 2020). "In breast cancer subtypes-ER-negative/HER2-negative, HER2-positive, and ER-positive/HER2-negative, the prevalence of PIK3CA mutations was 18%, 22%, and 37%, respectively." (PMID 33375317, 2020). "Targeting PI3K in CDK4/6-resistant breast cancer cells appears to be effective in both PIK3CA mutant and wild-type models, whereas targeting mTORC1 is effective in PIK3CA wild-type xenograft and one of two PIK3CA-mutant models." (PMID 32795346, 2020). "In contrast, mutations in the catalytic subunit of the Alpha isoform of the Phosphatidylinositol 4,5-Bisphosphate 3-Kinase (PIK3CA) were rarer in African American patients than in White breast cancer patients (20% vs 34%)." (PMID 32873298, 2020). "More recently, however, the importance of testing for BRCA and PIK3CA in selected patients with breast cancer has been established by the utility of PARP inhibitors and the PI3Ki alpelisib in selected subpopulations, respectively." (PMID 32637176, 2020). "The identification of several mutational cancer drivers, including ER, HER-2, PIK3CA, and CDK4/6, promoted the development of stratified medicine in breast cancer." (PMID 32902412, 2020). "Performing the same Outlier analyses, MYC and PIK3CA are overexpressed in 1 breast cancer data set each." (PMID 33176745, 2020). "A total of 4,895 breast cancer cases from 2015 to 2019 with available PIK3CA, AKT1, and PTEN NGS results were reviewed." (PMID 32983983, 2020). "PIK3R1 is in a DriveWays module containing PIK3CA and ERBB2, both of which are associated with breast cancer through the CMbreast reference set." (PMID 33319839, 2020). "The results of a cell viability assay revealed that antiproliferative activity measured by ATP was more potent in PIK3CA-wt/HER2+ breast cancer cell lines (red bars) than in PIK3CA–mut HER2+ breast cancer cell lines (blue bars)." (PMID 33303839, 2020). "Next, we examined the signaling pathways downstream of HER2 in the PIK3CA-wild-type or the PIK3CA-mutant HER2+ breast cancer cell lines treated with each inhibitor alone or in combination." (PMID 33303839, 2020).
breast cancer (continued). "Using the METABRIC dataset, we showed that increased FOXM1 expression correlates with poorer survival in PIK3CA mutant breast cancer patients and that survival is decreased in ER+ breast cancer patients with FOXM1 copy number gain." (PMID 32976773, 2020). "Currently, two assays have been approved by the US Food and Drug Administration for PIK3CA testing in advanced breast cancer." (PMID 32697890, 2020). "AZD8835 is an isoform-selective inhibitor of PI3Kα and PI3Kδ that preferentially inhibits cells growth with mutant PIK3CA status such as in estrogen receptor-positive (ER+) breast cancer cell lines and xenografts." (PMID 32194423, 2020). "TCGA analyses showed that MYC, PIK3CA, and CDKN2A/B are the most frequently amplified, mutated, and deleted genes, respectively, in breast cancer." (PMID 32498332, 2020). "In this paper, we demonstrate the genotyping of breast cancer variants with isothermal methods and CMOS technology, specifically detecting the PIK3CA p.H1047R variant." (PMID 32165708, 2020). "Taken together, these results suggest that ipatasertib treatment in combination with lapatinib has potential to overcome resistance HER2 therapy in patients with PIK3CA-mutant HER2+ breast cancers." (PMID 33303839, 2020). "In the luminal breast cancer cell line MCF-7,phosphatidylinositol-4,5-bisphosphate 3-kinase catalytic subunit alpha (PIK3CA) butnot AKT1 mutation increased sensitivity to MK22067." (PMID 33083527, 2020). "In this study, we also describe the clinical validation of the FoundationOne Liquid CDx assay, including large-scale comparisons with orthogonal clinical plasma- and tissue-genotyping methods, for both EGFR in NSCLC and PIK3CA in breast cancer." (PMID 32976510, 2020). "The PIK3CA mutations are highly associated with better responsive and survival outcomes of PI3K inhibitors in HR+ breast cancer." (PMID 32461963, 2020). "The clinical validity of the FoundationOne Liquid CDx assay to identify breast cancer patients harboring PIK3CA alterations eligible for treatment with alpelisib was assessed through retrospective testing of plasma samples." (PMID 32976510, 2020). "In patients with triple negative breast cancer, PIK3CA mutation rates were decreased (16%) compared to HR+/HER2 (42%) and HER2+ (31%) breast cancer subtypes." (PMID 33375317, 2020). "Due to the limited numbers of the commercially-available ER+/HER2+ breast cancer cell line, we used BT474 cells as a surrogate cell line model for PIK3CA-wt ER+/HER2+ breast cancer cell." (PMID 33303839, 2020). "Here we investigated the potential of these clinical imaging methods for detecting early response and resistance to PI3Kα inhibition in PIK3CA-driven ER+ breast cancer models." (PMID 32976773, 2020). "Alpelisib has been approved for the treatment of advanced breast cancer with PIK3CA mutation in positive hormone receptor, and clinical trials are investigating the possible response of TNBC with PIK3CA mutation to alpelisib." (PMID 33194720, 2020). "Meanwhile, PIK3CA mutations were more frequently detected from HR+/HER2+, HR−/HER2+ and HR+/HER2− breast cancer and less common in TNBC (P < 0.01), with detection rates of 50.0% (10/20), 44.4% (16/36), 33.0% (30/91), and 21.2% (29/137), respectively." (PMID 32695676, 2020).
breast cancer (continued). "In a mammary tumor model with conditional PIK3CA expression, Met amplification drove tumor recurrence following PIK3CA downregulation." (PMID 33024122, 2020). "Tumors that recurred after PIK3CA inactivation acquired focal amplification of MET or MYC in an in vivo mouse breast cancer model expressing PIK3CAH1047R34." (PMID 32409685, 2020). "In luminal breast cancers, the PI3K pathway is one of the most altered pathways, correlated with PIK3CA mutations, loss of PTEN, or downstream protein phosphorylation." (PMID 33375317, 2020). "For instance, breast cancer–initiating cells were eliminated in vitro and in vivo when Wnt/β-catenin signaling was inhibited with small molecule antagonist, and β-catenin inhibition sensitized PIK3CA-mutant breast cancer to PI3K inhibitors." (PMID 32373510, 2020). "At the same time, PIK3CA genes are mutated in 29% of the cases with subtype luminal B, in 39% of HER2-enriched breast cancers and only in 7% of basal-like tumors." (PMID 33375317, 2020). "PIK3CA gene mutations in the helical domain were correlated with TMB-H and poor prognosis in metastatic breast carcinomas with late-line therapies." (PMID 33996530, 2020). "In PIK3CA, the H1047R hot-spot has the highest probability of occurring in breast cancer (BRCA), whereas E545K has the highest occurrence in cervical cancer (CESC) and R88Q is more exclusive to endometrial cancer (UCEC)." (PMID 31796730, 2019). "PIK3CA, MAP 3 K1 and MAP 2 K4 are selected by five scores and known to be associated with breast cancer or other cancer types." (PMID 30704472, 2019). "For example, PIK3CA mutations, HER273 and ESR174 higher amplification were detected in breast cancers patients." (PMID 30873683, 2019). "Studies presented herein support a wider impact of mTORC1 signaling on Mcl-1 expression, highlighting the mTORC1-to-Mcl-1 axis in PIK3CA-wild type ER+ breast cancer cells (e.g. HCC1428)." (PMID 31595181, 2019). "Subsequent studies reported that PIK3CA mutations were highly associated with the morphology, race, ER status, PR status, and HER2 status in breast cancer." (PMID 31905960, 2019). "In order to bridge the gap between cell lines and Pan-cancer tumor samples, we extracted the BRCA samples and compared the TCI-predicted PIK3CA target DEGs in breast cancer tumors with that from Hart’s study." (PMID 31276486, 2019). "Of note, overexpression of wild type Pik3ca was insufficient to induce mammary tumours after 520 days." (PMID 31018529, 2019). "Collectively, these results demonstrate that PI3K p110α signalling contributes to RNMT dependency in breast cancer cell lines expressing oncogenic PIK3CA mutants." (PMID 30991934, 2019). "None of the samples showed a positive finding on OncoScan, despite the high prevalence of SCNAs in breast cancers, often involving deletion of PIK3CA or amplification of ERBB2." (PMID 30858924, 2019). "With regards to the first question, it is of relevance to note that mutation of PIK3CA is an early clonal event, occurring before WGD, in both breast cancer and in colon cancer." (PMID 31374965, 2019). "The MDA-MB-231 cell line is wild type for BRCA1 and PIK3CA, two genes often mutated in breast cancer, whereas the SUM159PT cell line contains wild type BRCA1 but also an activating PIK3CA mutation." (PMID 31362447, 2019).